ENSG00000231297 (novel transcript)
Gene: Long non-coding RNA gene on chromosome 6 (166,098,037 to 166,114,420, forward strand). Ensembl gene ENSG00000231297.
Gene Ontology:
Biological process: RNA processing
Cellular component: nucleolus